AFP (alpha fetoprotein)
Diseases named in the same sentence as AFP in open-access papers (continued):
Sharing a sentence is not in itself a finding about the gene and the disease.
tumor (continued). "AFP increases or decreases with tumor growth or subsides in about one-third of patients." (PMID 28767567, 2017). "We presumed that a reduction in the AFP level after TACE might indicate the preoperative TACE had reduced tumor activity, which in turn might lead to better results in the following resection procedure." (PMID 27880724, 2017). "Rats were killed at 0, 4, 8 and 12 weeks of experiment and blood and tissue samples were taken from all groups for the determination of tumour markers expression alpha-fetoprotein (AFP), transforming growth factor-β (TGF-β), M2-pyruvate kinase (M2-PK) and specific antigen for oval cells (OV-6)." (PMID 29268718, 2017). "Moreover, the combination of capsaicin and sorafenib decreased the expression of the HCC tumor marker alpha-fetoprotein (AFP) in the dissected tumors." (PMID 29152112, 2017). "Group D had the highest preoperative platelet counts, AST and AFP levels, and tumor sizes." (PMID 29258507, 2017). "On multivariate analysis, Child-Pugh classification, status of intrahepatic tumor, presence of distant metastasis, number and location of metastatic LNs, serum level of alpha fetoprotein (AFP), and the LN response to RT were significant prognostic factors for OS (p < 0.05 each)." (PMID 29212241, 2017). "Tumor number (p = 0.001) and size (p = 0.009), and alpha-fetoprotein (p = 0.049) were independent predictors of MVI used to create a prediction model, defined as: 0.293x(tumor number) + 0.283x(tumor size in cm) + 0.164xloge(alpha-fetoprotein in ng/ml) (c statistic = 0.743)." (PMID 28057916, 2017). "Also, tumor size (log-rank test: P=0.001), AFP (log-rank test: P=0.002), differentiation status (log-rank test: P=0.036) and TNM stage (log-rank test: P=0.004), and vascular invasion (log-rank test: P=0.000) were also shown to be associated with DFS." (PMID 28546230, 2017). "The results of the present study confirm that a combination of morphological tumor characteristics with serum alpha-fetoprotein concentration may be used for this purpose with moderate accuracy." (PMID 28057916, 2017). "The results revealed that preoperative Fib (P < 0.001), Child-Pugh stage (P = 0.037), AFP (P < 0.001), size of largest tumor (P < 0.001), tumor number (P < 0.001), macro-vascular invasion (P < 0.001), micro-vascular invasion (P < 0.001) and NLR (P = 0.013) were responsible for the DFS." (PMID 27935864, 2017). "The designed immunosensor might provide wide potential applications for the detection of AFP in clinical diagnosis and also can be applied in clinical detection of other tumor markers." (PMID 28186128, 2017). "Notably, the negative effect of microvascular invasion was only slightly above the level of significance following separate adjustment for the effects of size of the largest tumor and pre-transplant alpha-fetoprotein concentration." (PMID 28057916, 2017). "On the other hand, for children >1 year, a normal level of AFP often indicates a benign tumor." (PMID 28347316, 2017). "Multivariate analyses showed that a platelet count ≤ 100,000/mm3, a serum AFP level >20 ng/mL, a tumor size > 3 cm, the presence of vascular invasion, and the presence of EGV were the independent risk factors that predicted poor OS rates after curative therapies." (PMID 28209963, 2017). "A multivariate analysis disclosed that male gender, serum albumin ≤4.0 g/dL, bilirubin >1.6 mg/dL, a serum AFP level >20 ng/mL, a tumor size >3 cm, the presence of vascular invasion, as well as the presence of EGV, were the independent risk factors associated with poor OS rates." (PMID 28209963, 2017). "Patients with low circulating miR-193b had mainly alpha-fetoprotein (AFP) negative tumours, in line with previous reports of observed lower levels of AFP in CTNNB1-mutated HCC41." (PMID 27618837, 2017).
tumor (continued). "Furthermore, in terms of tumour biology NALFD patients had larger tumours at presentation although other factors such as number of tumours, extra hepatic spread were similar and AFP values were lower than HCV patients." (PMID 27634970, 2017). "The AUROC for prediction of microvascular invasion based on MVI index was 0.743 (SE 0.039), significantly higher than each of those observed for the three independent predictors: pre-transplant alpha-fetoprotein (p = 0.002), number of tumors (p = 0.022), and size of the largest tumor (p = 0.001)." (PMID 28057916, 2017). "No significant impact of microvascular invasion on 5-year recurrence-free survival was found following adjustment for the effects of number of tumors, size of the largest tumor, and pre-transplant alpha-fetoprotein in a 4-variable model (HR 1.56 95% CI 0.66–3.65; p = 0.307)." (PMID 28057916, 2017). "High percentage of AFP-L3 has been shown to be associated with poor differentiation and biologically malignant characteristics, worse liver function, and larger tumor mass; some experts thought that the AFP-L3/AFP ratio is more helpful in diagnosis and prognosis of HCC." (PMID 28540298, 2017). "Serum alpha-fetoprotein is a traditional tumour maker used in HCC screening and surveillance." (PMID 29207969, 2017). "Tumours with vascular invasion had a higher median AFP value (P = 0.002)." (PMID 29207969, 2017). "AFP level was evaluated against patient characteristics, tumour characteristics and survival." (PMID 29207969, 2017). "Clinical parameters such as alpha-fetoprotein (AFP), histologic grade, tumor numbers, tumor size, microvascular invasion, tumor thrombus, tumor stage (TNM), and the selection criteria for LT (Milan or UCSF criteria) have been reported as risk factors for HCC recurrence and prognosis after LT." (PMID 29162948, 2017). "In recent data from studies using alpha fetoprotein (AFP) peptide and protein DC vaccines in HCC, tumor-derived AFP had a negative impact on T cell proliferation, and gene expression arrays revealed that tumor AFP affected signaling pathways involved in lipid metabolism." (PMID 28716068, 2017). "AFP is related to tumor differentiation, whereas PIVKA-II is related to vascular invasion." (PMID 28830473, 2017). "Therefore, HCC patients with low INTS6 expression had a higher tendency to have high AFP levels, a poor pathology grade, and tumour recurrence." (PMID 28899352, 2017). "In addition, the AFP level and tumor differentiation were also significant predictors (P < 0.001, and P < 0.01, respectively)." (PMID 27418384, 2016). "Some tumor cells express AFP, hepatocyte antigen, and cytokeratin." (PMID 27488314, 2016). "The tumor was finally diagnosed as an ICC with aberrant expression of AFP." (PMID 27301956, 2016). "Independent factors that were unfavorable for survival after sorafenib treatment were as follows: no subsequent therapy, subsequent systemic therapies alone, Child-Pugh class B, Child-Pugh score 6, 400 ng/mL or higher serum AFP level, and discontinuation of sorafenib due to tumor progression." (PMID 27246496, 2016). "Various factors have been linked with worse outcome in HCC patients undergoing LT, such as tumor size, tumor number, degree of differentiation, hepatic microvascular invasion, hepatic macrovascular invasion, serum alpha-fetoprotein (AFP) levels, outside Milan criteria and infiltration." (PMID 27058525, 2016). "Thirty-two months after gastrectomy, tumor occurred metastasis and serum AFP level increased." (PMID 27631210, 2016). "Test of tumor biomarkers was performed to monitor alteration of serum AFP level." (PMID 27995033, 2016).
tumor (continued). "In patients with tumor size ≥2 cm, multivariable analysis showed that tumor recurrence was associated with increased PT-INR (HR=8.72 (95% CI: 2.06-36.91), p=0.003), and serum AFP level ≥20 ng/mL (HR=1.83 (95% CI: 1.17-2.86), p=0.009)." (PMID 27329596, 2016). "Univariate analysis showed that AFP value, tumor size, Gamma Glutamyl Transpeptidase (GGT) value, Alkaline phosphatase (ALP) value, and international normalized ratio (INR) value were independent risk factors affecting postoperative survival time among those HBsAg positive HCC patients." (PMID 26784252, 2016). "Additionally, as a tumor marker, AFP served as an important indicator for HCC diagnosis and patient follow-up." (PMID 27389277, 2016). "The differences for pre-transplant status, determined based on the number of tumor nodules, size of the largest tumor, preoperative AFP level, and neoadjuvant treatment may have influenced the survival rates significantly." (PMID 27225666, 2016). "High serum AFP levels at the time of diagnosis of HCC were associated with worse clinicopathologic features and poor outcomes; larger tumor size, bilobar involvement, massive or diffuse tumor types, portal vein thrombosis, advanced stages, early recurrence and poor overall survival." (PMID 27304617, 2016). "In addition, low ASK1 and HNF4α expression were more likely in human HCC specimens containing high levels of AFP, tumor diameter > 5 cm and advanced tumor stage, vice versa." (PMID 27050273, 2016). "AFP is a classic tumor marker is used to diagnose HCC in early stages." (PMID 26824501, 2016). "Interestingly, serum AFP level 1 month after the surgery declined to 1.99 ng/mL, used as tumor marker for recurrence." (PMID 26976278, 2016). "Tumour markers after chemotherapy improved remarkably with AFP of 17 ng/mL and LDH of 477 iu/L." (PMID 27807495, 2016). "In addition, a number of clinicopathologic features have been identified as prognostic indicators for HCC patients, such as vascular invasion, tumor size, the level of serum a-fetoprotein (AFP) and bilirubin." (PMID 26716411, 2016). "Consequently, patients with FL-HCC rarely have elevated serum levels of AFP, and AFP has been demonstrated only in the minority of patients with FL-HCC in the tumor immunohistochemically." (PMID 27215576, 2016). "Furthermore, we revealed that SOX9 expression was significantly correlated with the serum OPN level in human cases, and that its efficacy in identifying SOX9 expression in the tumors was superior to conventional tumor markers such as AFP and PIVKA-II." (PMID 27457505, 2016). "Initial tumour markers revealed an AFP of 22,854 ng/mL, HCG of <1 mIU/mL, and LDH of 463 IU/L." (PMID 27830100, 2016). "The average tumor size was 5.86 cm, and 3 subjects have AFP level higher than 400 ng/ml." (PMID 27769059, 2016). "In addition to some routinely applied tumor markers, such as α-Fetoprotein (AFP), CEA, CA19-9 and carbohydrate antigen 72-4 (CA72-4), there are still many other tumor markers used in different hospitals." (PMID 27097114, 2016). "AFP is a commonly used tumor marker for the early screening of primary HCC." (PMID 27390551, 2016). "The result shows that low SOD2 protein expression (p = 0.005), higher serum AFP (p = 0.002), larger tumor size (p = 0.010), multiple tumors (p < 0.001), tumor embolus (p = 0.004) advanced TNM (p = 0.001) and BCLC stage (p < 0.001) are predictors for poor OS of HCC patients." (PMID 27221200, 2016). "By univariate analysis, controlled intrahepatic tumor, controlled extrahepatic metastasis except adrenal metastasis, tumor size less than 4.7 cm (median tumor size), alpha-fetoprotein value less than 400 ng/mL, and Child-Pugh class A were related to favorable OS." (PMID 27022932, 2016). "The prognostic role of tumor markers like AFP in HCC has been studied extensively." (PMID 26872727, 2016).
tumor (continued). "In addition, high PLR was not significantly correlated with the presence of vascular invasion, tumor multifocality, poor tumor grade or high level of serum AFP (>400 ng/ml)." (PMID 27739490, 2016). "More than 70 % of HCC patients have AFP secretion, and a high serum level of AFP (>400 ng/mL) may be an indirect measure of tumor burden." (PMID 26936459, 2016). "However, current clinicopathologic factors, such as α-fetoprotein (AFP), tumor node metastasis (TNM) stage, and Barcelona clinic liver cancer (BCLC) stage, cannot accurately predict the outcome of HCC patients." (PMID 27689999, 2016). "Moreover, on day 35 after tumor implantation, the AFP concentration in the vehicle-treated group was 4,780,122 ± 2,929,242 ng/mL and that in the CBT-143-S-F6F7-treated group was 2,705,733 ± 1,463,381 ng/mL (P = 0.06)." (PMID 27502492, 2016). "Multivariate analysis showed that preoperative AFP (p = 0.010), the largest tumor size >5 cm (p < 0.001), multiple tumor nodules (≤3) (p < 0.001), microscopic portal vein thrombosis (p = 0.014), and macroscopic vascular invasion (p = 0.017) were the independent prognostic factors for poor OS." (PMID 26936459, 2016). "When those patients were included for the analysis of factors associated with OS, univariate analysis showed that total bilirubin (TBIL), ALB, AFP, Child-Pugh score, tumor size, TNM stage, PD1 +8669 A/G and TIM3 −1516 G/T polymorphisms were significantly associated with patients' survival." (PMID 27034168, 2016). "Hence, FDG standardized uptake value (SUV) in HCC, as compared to adjacent normal liver (tumour-to-liver ratio), reflects tumour aggressiveness, including histological tumour grade and AFP levels, which in turn correlate with outcome." (PMID 26883745, 2016). "In our study, some recognized factors, such as tumor size, AFP, and vascular invasion are not the independent risk factors for TTR and OS for HCC." (PMID 27683106, 2016). "Moreover, in vitro cytotoxic T-lymphocyte assays and in vivo tumor preventive experiments clearly showed the higher antitumor effects of HSP70-P/AFP-P against AFP-expressing tumors." (PMID 27713135, 2016). "In the present study, we performed a weighted gene co-expression network analysis (WGCNA) for HCC using mRNA- and lncRNA-seq data to investigate the association between differentially expressed genes (DEGs) and HCC clinical traits, e.g., tumor grade and the α-fetoprotein (AFP) level." (PMID 27220887, 2016). "Unfortunately, the main serum tumor markers including alpha-fetoprotein (AFP), lens culinaris agglutinin-reactive AFP (AFP-L3), des-gamma carboxyprothrombin (DCP) and glypican-3 (GPC3), failed to reach the optimal results when tested in the surveillance and early detection." (PMID 26933386, 2016). "However, After multivariate analysis, we catch that the independent related factors for both DFS were AFP, tumor size, tumor number, PVTT, ANRI and Neutrophil." (PMID 27472390, 2016). "Strong albeit focal reactivity for GPC3 and AFP was seen in the yolk sac tumor component." (PMID 26880963, 2016). "The univariate survival analysis revealed the following predictors of mortality in patients with solitary large HCC: serum albumin < 4 g/dL, bilirubin ≥ 1 mg/dL, α-fetoprotein (AFP) level ≥ 400 ng/mL, performance status ≥ 1, tumor size > 10 cm, presence of PVTT, and TACE treatment (all p<0.01)." (PMID 27176037, 2016). "However, there were significant inverse correlations between TIP30 expression and serum AFP level, tumor differentiation, and serum HBV infection." (PMID 27418384, 2016). "Importantly, mRNA expression of the tumor marker alpha‐fetoprotein (AFP) decreased after DMSO treatment, with a significant decrease observed after 7 days that persisted up to 21 days of treatment." (PMID 27803313, 2016).
tumor (continued). "Univariate survival analysis for patients in the propensity score model showed the following predictors of poor prognosis: age < 65 years, serum albumin < 4 g/dL, bilirubin ≥ 1 mg/dL, AFP level ≥ 400 ng/mL, tumor size > 10 cm, presence of PVTT, and TACE treatment (all p<0.1)." (PMID 27176037, 2016). "That is why tumor cells producing M-CSF and VEGF are different from tumor cells producing AFP." (PMID 27966626, 2016). "Alpha-fetoprotein (AFP), AFP lectin fraction (AFP-L3) and proteins induced through vitamin K deficiency or antagonist-II (PIVKA-II), which is also known as des-γ-carboxy prothrombin (DCP), have been used as conventional serum tumor markers." (PMID 27462777, 2016). "TACE can improve tumor-free survival rates in patients with a tumor diameter of 3–10 cm, positive AFP value and vascular invasion or patients with a tumor diameter greater than 10 cm, AFP positivity, and multiple satellite nodules associated with vascular invasion." (PMID 27038790, 2016). "Furthermore, by univariate analysis of the Cox proportional-hazard model, CTSB expression, serum AFP, tumor size, metastasis/recurrence, and TNM staging were found to be associated with an increased risk of death by HCC." (PMID 26896959, 2016). "Of the tumor markers tested, AFP was 12,310 ng/mL (normal level: 0 ng/mL −20 ng/mL)." (PMID 27301956, 2016). "In univariate analysis, AFP (P = 0.041), tumor size (P = 0.002), and response to treatment (P = 0.001) were significantly associated with OS; and AFP (P = 0.013), tumor size (P = 0.000), tumor thrombus (P = 0.018), and response to treatment (P = 0.005) were significantly associated with PFS." (PMID 27227954, 2016). "Using univariate analysis, we discovered many significant prognostic factors for DFS or OS of HCC, including HBsAg, gender, AFP, AST, Neutrophil, CLIP score, TNM stages, PVTT, tumor size, tumor number, poor differentiation, intraoperative blood loss, NLR, PLR, ALRI, APRI and ANRI." (PMID 27472390, 2016). "After multivariate analysis, we found that AFP, tumor size, tumor number, PVTT, ANRI and Neutrophil were significant independent predictors of DFS (all P < 0.05), while tumor number, PVTT, ANRI, CLIP score, AST and NLR were significant independent predictors of OS (all P < 0.05)." (PMID 27472390, 2016). "Therefore, single-nodule SHCC patients with higher preoperative NLR and lower AFP (≤400 ng/mL) still require closer follow-up since they have more possibilities to suffer from tumor recurrence." (PMID 26328917, 2015). "Moreover, the expression of miR-1236 was lower in HCC tissues relative to adjacent non-tumor tissues, which is in contrast to the expression of AFP." (PMID 25714026, 2015). "Importantly, we also found that PKM2 overexpression was correlated with serum AFP concentration, tumor size, microvascular invasion, poor differentiation, and higher TNM stage." (PMID 25576919, 2015). "In this study, our results demonstrated that HBx stimulates the neoplastic transformation of normal cells and tumor induction by AFP triggering of the PI3K/mTOR signal to promote expression of Src, Ras, and CXCR4, which are known to promote the progression, invasion, and metastasis of cancer cells." (PMID 25682869, 2015). "Similarly, in our patients we found the same correlation when we compared the serum AFP values with BCLC tumor stage." (PMID 26122937, 2015). "Patients with AFP levels >1000 mcg/l are at an extremely high risk of recurrent disease following transplantation, irrespective of the tumor size." (PMID 29201680, 2015). "However, our research showed that MEG3 elevated in HCC tumor tissues and correlated with AFP elevation in human." (PMID 26136615, 2015). "Multivariate analysis showed that AFP, diameter of largest lesion, tumor number and vascular invasion were independent prognostic factors for OS, along with NLR (HR 1.32, 95% CI 1.07–1.62, P = 0.009), or dNLR (HR 1.26 95% CI 1.03–1.52, P = 0.022), or M/GLR (HR 1.40 95%CI 1.14–1.71, P = 0.001)." (PMID 26486016, 2015).